NLRP3 (NLR family pyrin domain containing 3)
Diseases named in the same sentence as NLRP3 in open-access papers (continued):
Sharing a sentence is not in itself a finding about the gene and the disease.
colitis (continued). "The function of UAF1 in the mouse model of colitis was further examined by NLRP3." (PMID 39966502, 2025). "A dual-acting synthetic molecule and inhibitor termed 10 v has recently been suggested to attenuate in vivo induced-colitis by disrupting ASC interaction for proper NLRP3 and AIM-2 function as well as signal transducers and activators of transcription (STAT) signaling pathways." (PMID 40869366, 2025). "Our study aimed to examine the levels of ⍺7nAChR for the cholinergic activity and NLRP3 inflammasome in healthy individuals, individuals with GI tumors (gastric and colorectal cancers), and individuals diagnosed with colitis, and to elucidate the correlation between these parameters and diseases." (PMID 41003004, 2025). "The current investigation demonstrated that Lac16 could alleviate colitis by suppressing NLRP3 inflammasome overactivation via microbiota-derived isobutyric acid." (PMID 41171006, 2025). "Mice without ASC, caspase-1, or NLRP3 had more severe colitis and tumorigenesis in colitis-associated cancer models." (PMID 40141358, 2025). "Besides, we also determined the NLRP3 inflammasome inhibitory role in dextran sulfate sodium (DSS)‐induced colitis." (PMID 40349158, 2025). "Studies show that in mice, a lack of NLRP3 can lead to colitis and colitis‐associated colorectal cancer (CRC) when treated with azoxymethan." (PMID 40671967, 2025). "NF-κB/NLRP3 appears to be a critical signaling pathway involved in the regulation of colitis." (PMID 41467030, 2025). "Also, presented with VEO-IBD, the deficiency of the receptor-interacting protein kinase 1 (RIPK1) gene inhibits NLRP3 inflammasome activation upon lipopolysaccharide stimulation, participating in human colitis." (PMID 41149694, 2025). "Similarly, PTX treatment resulted in significant reductions of 50.08% in mTOR (F = 528.4, p = 0.02) and 53.93% in NLRP3 expression (F = 66.14, p = 0.006) versus the colitis group." (PMID 40387460, 2025). "The study revealed significantly less colitis and mortality in mice lacking NLRP3 gene expression; however, close and frequent exposure to wild-type mice led to susceptibility of the knockout mice to colitis." (PMID 41340115, 2025). "The anti-inflammatory and the antioxidant's efficacy of TXM peptides was evaluated using the tetra peptides TXM-CB13 both in-vivo, in a dextran sulfate sodium (DSS)-induced colitis mouse model, and in vitro, in LPS-induced NLRP3 inflammasome activation in RAW264.7 macrophages." (PMID 41129928, 2025). "The study indicated that GB1 might serve as a natural NLRP3 inhibitor, thereby providing a new strategy for alternative colitis treatment." (PMID 40362256, 2025). "Pharmacological inhibition of NLRP3 effectively abrogated rPrdx1-induced exacerbation of colitis." (PMID 40715057, 2025). "The protective effects of TXM-CB13 in both DSS-induced colitis in mice and LPS-induced NLRP3 activation in RAW264.7 macrophages highlights a promising dual anti-inflammatory and antioxidant mechanisms, indicating its potential as a therapeutic candidate for inflammatory bowel disease." (PMID 41129928, 2025). "Ile triggers the NLRP3 inflammasome pathway to exacerbate colitis." (PMID 41394102, 2025). "In addition, NLRP3 knockout (NLRP3-/-) mice eliminated the protective effect of A. muciniphila in DSS-induced colitis." (PMID 41488633, 2025). "The stimulation of NLRP3 by P. mirabilis plays a crucial role in exacerbating colitis." (PMID 41149694, 2025). "Furthermore, MHV-68 infection activated pyroptosis by upregulating gasdermin D, NLRP3, interleukin-1β, and interleukin-18 in colonic tissues and peritoneal macrophages of mice with colitis." (PMID 40041420, 2025). "Their ability to influence inflammasome pathways, especially NLRP3, has shown effectiveness in reducing excessive inflammation and mitigating chronic inflammatory conditions such as IgA nephropathy, cardiac fibrosis, and colitis." (PMID 40076871, 2025).
colitis (continued). "The experiments results showed that ATF may inhibit the occurrence of colitis phenomena, including weight loss, diarrhea, blood in stool, and colon shortening in UC mice by modulating the microbiota-LPS/TLR4/NF-κB/NLRP3 signaling axis." (PMID 40130239, 2025). "Notably, knockdown of VANGL2 or MARCH8 effectively enhanced NLRP3 inflammasome activation in PBMCs from healthy individuals, but not from IBD patients, which strongly suggest a role for VANGL2 in anti-colitis progression via the NLRP3 inflammasome pathway." (PMID 39899477, 2025). "In summary, our findings demonstrate that Lac16 alleviates DSS-induced colitis by preserving intestinal barrier integrity, reducing inflammation, regulating macrophage polarization, modulating NLRP3 inflammasome activation, and maintaining gut microbiota homeostasis." (PMID 41171006, 2025). "In addition, PAL protected mice against DSS-induced colitis by inhibiting NLRP3 inflammasome activation through promoting autophagy." (PMID 39096445, 2025). "Further studies have demonstrated that NLRP3 deficiency downregulates glucose transporter protein 1 (GLUT1) expression and glycolytic activity in MSCs, leading to decreased IL-10 production and reduced therapeutic efficacy against DSS-induced colitis." (PMID 40433382, 2025). "Subsequently, the activation of NLRP3 inflammasome in colons of colitis mice was assessed." (PMID 40919130, 2025). "Based on these findings, we hypothesize that inactivated AKK PROBIO may attenuate the initiation and progression of colitis by modulating the TLR4/NF-κB/NLRP3 signaling axis." (PMID 41376001, 2025). "The findings suggested that METTL3, as an m6A-forming enzyme, could regulate UAF1 mRNA, promoting inflammation in colitis through NLRP3 induction." (PMID 39966502, 2025). "In addition, punicalagin has been shown to exert anti-inflammatory and microbiota-modulating effects in murine colitis models, as well as attenuating ventricular remodeling after acute myocardial infarction through regulation of the NLRP3/caspase-1 pathway." (PMID 40362057, 2025). "Collectively, these findings exhibited that bigelovin could block the activation of NLRP3 inflammasome in vivo and mitigate the severity of silicotic and colitis mice." (PMID 40349158, 2025). "In addition, previous studies have shown that downregulating NLRP3 expression can improve intestinal inflammation, and NLRP3 knockout (KO) mice are protected from DSS-induced colitis." (PMID 39272608, 2024). "Furthermore, there must be other mechanisms, such as the NF‐κB and NLRP3/caspase‐1 signaling pathways, by which SH ameliorates colitis." (PMID 38882491, 2024). "Moreover, the treatment with probiotic microcapsules suppressed the activation of the NLRP3 inflammasome signaling pathway in the context of DSS-induced colitis." (PMID 38613088, 2024). "Additionally, HU308, via the modulation of CB2 receptors, was shown to reduce DSS-induced colitis by inhibiting the nucleotide-binding domain and leucine-rich repeat protein 3 (NLRP3) inflammasome in macrophages." (PMID 39682761, 2024). "DSS-induced colitis in mice is an experimental NLRP3 inflammasome-related inflammation model." (PMID 39701924, 2024). "Notably, (R,R)-BD-AcAc2 improved experimental colitis, targeting the priming and activation of the NLRP3 inflammasome and its downstream signaling molecules, inhibiting pyroptosis and inducing autophagy." (PMID 39684769, 2024). "Furthermore, our previous studies demonstrated that inducing autophagy by activating the cannabinoid receptor 2 inhibited NLRP3 inflammasome activation in colitis and EAE mouse models." (PMID 38354108, 2024). "Thus, targeting the NLRP3 inflammasome via up-regulating the SCFAs is at least one of the mechanisms employed by QHF to exert its anti-colitis effects." (PMID 38257292, 2024). "This molecule inhibited NLRP3 assembly and activation, reducing experimental colitis." (PMID 39684769, 2024).
colitis (continued). "Additionally, recent in vitro evidence showed that butyrate and a butyrogenic GM can worse the inflammatory process in colitis through an NLRP3 inflammasome-dependent process." (PMID 38732048, 2024). "Further evidence suggested that the caffeic acid phenethyl ester (CAPE) administration blocked the interaction between NLRP3 inflammasomes and DUB COP9 signalosome 5 (CSN5) in azoxymethane (AOM)/DSS-induced colitis-associated colorectal cancer (CAC) mouse colon tissues." (PMID 38193803, 2024). "Based on results that DCA reduced the inflammatory response of NLRP3 inflammasome and oxidative stress in oxazolone colitis model, we tended to score DCA impact on DAI and the integrity of colon tissue using histopathological colon sectioning and staining, followed by colon ulceration scoring." (PMID 37902927, 2024). "Additionally, Rev‐erbα integrates experimental colitis by repressing the nuclear factor (NF)‐κB/NLRP3 axis." (PMID 39045886, 2024). "Indeed, galangin was shown to potentially alleviate colitis by inhibiting HSP90β and perturbing fatty acid synthesis-mediated NLRP3 inflammasome activation." (PMID 39494333, 2024). "Akkermansia muciniphila produces acetate and propionate; furthermore, a recent study revealed that Amuc_2109, an enzyme secreted by A. muciniphila, attenuates dextran sodium sulfate-induced colitis, increases TJ protein expression, and decreases NLRP3 inflammatory vesicle expression in mice." (PMID 39444688, 2024). "These natural compounds improved inflammatory conditions and colon tissue damage in a DSS-induced colitis mouse model by regulating the NF-κB signal and NLRP3 inflammasome, as well as the damage to the colon epithelial barrier, restoring the tight junction (TJ) architecture." (PMID 39684769, 2024). "Administration of IL-1β to NLRP3-null mice has shown protection against oxazolone-induced colitis." (PMID 39769450, 2024). "In addition to reducing mitochondrial ROS generation, this molecule can inhibit the binding of TXNIP to NLRP3 and intervene in the activation of NLRP3 inflammasome, as shown in colitis of mice induced by dextran sulfate sodium (DSS)." (PMID 38256186, 2024). "The NLRP3 inflammasome plays a crucial role in DSS-induced murine colitis." (PMID 39061864, 2024). "In our study, we tested Nlrp3 expression levels during the progression of colitis." (PMID 38879692, 2024). "In the colitis model, the colonic inflammation grade was significantly increased in NLRP3-deficient mice but not in mice administered glyburide." (PMID 39519191, 2024). "Additionally, there are also some bacterial metabolism products, such as short-chain fatty acids (SCFAs), that have the capacity to activate colonic epithelial cells within NLRP3 inflammatory vesicles, thereby contributing to the prevention of colitis." (PMID 39687875, 2024). "Also, these compounds possess anti-inflammatory properties, suppressing inflammatory pathways involved in colitis and inhibiting the NLRP3 inflammasome, thereby reducing pro-inflammatory cytokines like IL-1β, IL-6, and TNF-α." (PMID 39061864, 2024). "Therefore, NLRP3 inflammasomes play a crucial role in preventing and treating colitis, potentially therapeutic targets for IBD." (PMID 38455052, 2024). "It was proved that curcumin could strongly alleviate DSS-induced experimental colitis by inhibiting NLRP3 inflammasome activation." (PMID 37089942, 2023). "In colitis-associated cancer models, mice lacking ASC, caspase-1, or NLRP3 show more severe colitis and accentuated tumorigenesis." (PMID 36932407, 2023). "Furthermore, we investigated the impacts of circPRKAR1B knockdown on autophagy and pyroptosis mediated by the NLRP3 inflammasome in experimental colitis models." (PMID 37679886, 2023). "PAP-1, also named 5-(4-phenoxybutoxy) PS, might mitigate the severity of colitis in mice via inhibition of the NLRP3 inflammasome pathway." (PMID 37685978, 2023).
colitis (continued). "In an in vitro and in vivo study using IFN-γ-stimulated intestinal macrophages and DSS-induced C57BL/6 mice model of colitis, respectively, Ruan and Zha assessed the roles of moronic acid against a triterpenoid richly found in Pistacia chinensis, against NLRP3 activation during IBD." (PMID 37367886, 2023). "In addition, MCC950, a chemical NLRP3 inhibitor, can significantly suppress the release of the pro-inflammatory cytokines IL-1β, IL-18, and IL-1α in colitis." (PMID 37240022, 2023). "Previous research showed that GSKJ4 could impede the inflammatory response by inhibiting KDM6B and augmenting the NLRP3 transcriptional suppression in colitis." (PMID 37974225, 2023). "Therefore, we used an animal model of 2,4,6-trinitrobenzene sulfonic acid (TNBS)-induced CD-like colitis to investigate protective effects of maqui extract through monitoring NLRP3 inflammasome and MC activation in colon tissue." (PMID 38283356, 2023). "Notably, some NLRP3 nature original inhibitors can improve colitis by restraining the activation of NLRP3." (PMID 37370025, 2023). "We next also addressed the function of NLRP3 in KLPJ-mediated colitis." (PMID 36436756, 2023). "In the current study, the experimental model of CD-like colitis has a high expression of proinflammatory cytokines, demonstrating that inflammasome NLRP3 pathway may have a relevant role in the inflammatory process." (PMID 38283356, 2023). "Therefore, it is essential to investigate the interplay among GM, BAs, and NLRP3 inflammasome in the context of colitis." (PMID 37674245, 2023). "However, hypoxia counteracts inflammation through the downregulation of the binding of mTOR and NLRP3 and the activation of autophagy, which is protective in mouse models of colitis." (PMID 37830626, 2023). "hucMSC-Ex could attenuate colitis by regulating macrophage pyroptosis via the miR-378a-5p/NLRP3 axis." (PMID 36845967, 2023). "In addition, a small molecule inhibitor of NLRP3, MCC950, showed potential in preventing the activation of the NLRP3 inflammasome and effectiveness in a colitis mouse model." (PMID 37833958, 2023). "To determine whether ECE could affect the NLRP3 inflammasome pathway in DSS-induced colitis, we measured NLRP3 activation in colon tissues using qRT-PCR and Western blot, respectively." (PMID 38138587, 2023). "Baill against NLRP3 activation in a DSS-induced C57BL/6 mice model of colitis." (PMID 37367886, 2023). "Given that CGA did not modulate colitis severity in either macrophage-deleted or CY-09-treated mice, we next considered the possibility that the protective effect of CGA against colitis might be achieved by macrophage-NLRP3 axis." (PMID 37813835, 2023). "This accords with a previous report identifying NLRP3 functions in DSS-induced colitis." (PMID 36875104, 2023). "Moreover, mice deficient in inflammasome components such as NLRP3, caspase-1, or ASC have an enhanced susceptibility to DSS-colitis." (PMID 37681916, 2023). "In addition, in the oxazolone-induced mouse UC model, NLRP3 knockout mice have more severe colitis, as indicated by increased Th2 cytokine expression and decreased production of mature IL-1β and IL-18." (PMID 37370025, 2023). "In non-immune cells such as human umbilical cord blood-derived mesenchymal stem cells (hUCB-MSCs), in vitro as well as in DSS-induced colitis, NLRP3 inflammasome activation improved the protective anti-inflammatory abilities of several immune cells, including macrophages." (PMID 37681916, 2023). "Current study evidence has shown that large amounts of the NLRP3 inflammasome exacerbate colitis." (PMID 37505716, 2023). "In addition, it has been reported that the administration of an herbal extract to mice with DSS-induced colitis enhances mitophagy, leading to NLRP3 inflammasome inhibition, and subsequently the amelioration of colitis." (PMID 37298868, 2023). "For the pathogenesis of colitis, the detailed roles of the NLRP3 inflammasome are controversial." (PMID 37970386, 2023).
colitis (continued). "Indeed, miR-223 suppressed NLRP3 expression, reduced IL-1β production, and thus ameliorated the experimental colitis." (PMID 37681916, 2023). "We provide the first evidence that chlorogenic acid mitigate colitis and prevent colitis-caused dysbiosis through inhibiting PKM2-dependent glycolysis, and thereby blocking Nlrp3 activation to shift the inflammatory M1 macrophage toward the anti-inflammatory M2 phenotype." (PMID 37813835, 2023). "Furthermore, NLRP3 has a prominent role in intestinal stromal cells in providing resistance to DSS-induced colitis." (PMID 37519301, 2023). "This suggests that inhibiting macrophage NF-κB signaling and NLRP3 inflammasome activation might improve dextran sulfate sodium (DSS)-induced colitis." (PMID 37284442, 2023). "However, DSS-induced colitis was attenuated in Nlrp3-/- mice and ameliorated by caspase-1 inhibition." (PMID 37081882, 2023). "According to a study in 2018, curcumin could alleviate DSS-induced colitis in mice via the inhibition of the NLRP3 inflammasome with a reduction in IL-1β and IL-6." (PMID 37833958, 2023). "However, the role of the NLRP3 inflammasome in acute intestinal inflammation is controversial, as contradictory studies have identified opposing functions during experimental colitis." (PMID 37681916, 2023). "Inhibition or knockdown of the NLRP3 inflammasome could alleviate the severity of DSS-induced colitis, control the release of IL-1β and IL-18, and suppress the inflammatory response of UC." (PMID 36762118, 2023). "NLRP3 inflammasome activation plays an important role in colitis." (PMID 36840499, 2023). "Finally, high cholesterol and saturated fatty acids diets exacerbate NLRP3 activation, thereby promoting colitis, cancer, as well as compromising glucose metabolism." (PMID 37891577, 2023). "In the present study, we examined the role of Ononin in mouse colitis induced by dextran sulfate sodium (DSS)‐induced colitis and found that Ononin activated mitophagy, inhibiting the formation of NLRP3 inflammasome and the production of inflammatory cytokines and mediators." (PMID 36840499, 2023). "Furthermore, the anti-colitis activity of shionone was also observed with a reduction in inflammation and inflammatory factors such as NLRP3, caspase 1, and IL-1β in the colon." (PMID 38202771, 2023). "In addition, Akkermansia muciniphila activates NLRP3 expression to ameliorate symptoms in DSS-induced colitis." (PMID 36558471, 2022). "Furthermore, it has been recently reported that RRx-001 ameliorates systemic inflammation by inhibiting the assembly of NLRP3 inflammasome in mice with colitis and experimental autoimmune encephalomyelitis (EAE)." (PMID 35462935, 2022). "Moreover, in this study, the anti-NLRP3 inflammasome activity of carnosic acid has shown to be comparable with those of 5-aminosalicylic acid, a standard of care for the treatment of colitis disease." (PMID 35276849, 2022). "In addition, the chalcone analog screened by the hit-to-lead attenuated the symptoms in the NLRP3 inflammasome-mediating diseases models, such as dextran sulfate sodium-induced colitis and LPS-induced sepsis." (PMID 36577816, 2022). "A growing body of evidence suggests that some natural products might act by targeting the NLRP3 inflammasome to affect colonic inflammation in colitis models." (PMID 36199683, 2022). "Pharmacological inhibition of the NLRP3 inflammasome plays a protective role in colitis." (PMID 35330829, 2022). "These mice were less susceptible to DSS-induced colitis than non-chimeric Nlrp3-/- mice, comparable to WT mice." (PMID 35911682, 2022). "Our previous study showed that C646, an inhibitor of histone acetyltransferase p300, has a protective role in dextran sulfate sodium (DSS)-induced colitis by targeting the NLRP3 inflammasome, making us further study the inhibitors of histone deacetylases (HDACs) in the treatment of colitis." (PMID 35330829, 2022). "NLRP3 also plays a protective role in the probiotic-based therapy of colitis." (PMID 36389791, 2022).